H4C12 (H4 clustered histone 12)
Description:
Core component of nucleosome. Nucleosomes wrap and compact DNA into chromatin, limiting DNA accessibility to the cellular machineries which require DNA as a template. Histones thereby play a central role in transcription regulation, DNA repair, DNA replication and chromosomal stability. DNA accessibility is regulated via a complex set of post-translational modifications of histones, also called histone code, and nucleosome remodeling.
Synonyms: H4/D; H4FD; HIST1H4K; H4F2iii; dJ160A22.1
Target class: Other nuclear protein
Gene: Protein-coding gene on chromosome 6 (27,830,918 to 27,831,560, reverse strand). Ensembl gene ENSG00000273542.
Subcellular location: Nucleus; Chromosome
Pathways (Reactome):
Gene expression (Transcription): B-WICH complex positively regulates rRNA expression; DNA methylation; ERCC6 (CSB) and EHMT2 (G9a) positively regulate rRNA expression; MLL4 and MLL3 complexes regulate expression of PPARG target genes in adipogenesis and hepatic steatosis; NoRC negatively regulates rRNA expression; PRC2 methylates histones and DNA; RNA Polymerase I Promoter Escape; RNA Polymerase I Promoter Opening; RUNX1 regulates genes involved in megakaryocyte differentiation and platelet function; RUNX1 regulates transcription of genes involved in differentiation of HSCs; Regulation of endogenous retroelements by KRAB-ZFP proteins; Regulation of endogenous retroelements by Piwi-interacting RNAs (piRNAs); Regulation of endogenous retroelements by the Human Silencing Hub (HUSH) complex; SIRT1 negatively regulates rRNA expression; Transcriptional regulation by small RNAs
Chromatin organization: CHD1 and CHD2 subfamily; CHD6, CHD7, CHD8, CHD9 subfamily; ChAHP complex assembly; HATs acetylate histones; HDACs deacetylate histones; HDMs demethylate histones; Interaction of NuRD complexes with transcription factors; NuRD complex assembly; PKMTs methylate histone lysines; RMTs methylate histone arginines
DNA Repair: Cleavage of the damaged purine; Cleavage of the damaged pyrimidine; Nonhomologous End-Joining (NHEJ); Processing of DNA double-strand break ends; Recognition and association of DNA glycosylase with site containing an affected purine; Recognition and association of DNA glycosylase with site containing an affected pyrimidine; Recruitment and ATM-mediated phosphorylation of repair and signaling proteins at DNA double strand breaks
Cell Cycle: Condensation of Prophase Chromosomes; Deposition of new CENPA-containing nucleosomes at the centromere; G2/M DNA damage checkpoint; Inhibition of DNA recombination at telomere; Packaging Of Telomere Ends
Developmental Biology: Activation of anterior HOX genes in hindbrain development during early embryogenesis; Chromatin modifications during the maternal to zygotic transition (MZT); Replacement of protamines by nucleosomes in the male pronucleus
and 20 more pathways
Gene Ontology:
Molecular function: protein binding; RNA binding; structural constituent of chromatin; DNA binding; protein heterodimerization activity
Biological process: negative regulation of megakaryocyte differentiation; nucleosome assembly; chromatin organization; protein localization to CENP-A containing chromatin; telomere organization
Cellular component: CENP-A containing nucleosome; chromosome, telomeric region; extracellular exosome; membrane; nucleoplasm; nucleosome; nucleus; protein-containing complex; extracellular region; chromosome
Genetic constraint (gnomAD): Loss-of-function variants: 3 observed, 3.47 expected, observed/expected ratio (o/e) 0.86, 90% interval 0.38 to 1.8. That is too few expected variants to judge how well the gene tolerates losing a copy. Missense variants: 81 observed, 122.16 expected, observed/expected ratio (o/e) 0.66, 90% interval 0.55 to 0.8. Synonymous variants: 71 observed, 48.62 expected, observed/expected ratio (o/e) 1.46, 90% interval 1.21 to 1.77.
Homologues: Orthologues: chimpanzee H4C6 (100% identical), mouse H4c12 (100% identical), tropical clawed frog h4c3 (100% identical). Paralogues in human: H4C1 (100% identical), H4C11 (100% identical), H4C13 (100% identical), H4C14 (100% identical), H4C15 (100% identical), H4C16 (100% identical), H4C2 (100% identical), H4C3 (100% identical), H4C4 (100% identical), H4C5 (100% identical), H4C6 (100% identical), H4C8 (100% identical), and 2 more.
Diseases named in the same sentence as H4C12 in open-access papers:
H4C12 is named in the same sentence as 1 disease in open-access papers, as found by Europe PMC text mining. Sharing a sentence is not in itself a finding about the gene and the disease.
H4C12 shares sentences with these, for which no sentence is quoted: systemic lupus erythematosus (1 paper).